HLA-DRB1 (major histocompatibility complex, class II, DR beta 1)
Diseases named in the same sentence as HLA-DRB1 in open-access papers (continued):
Sharing a sentence is not in itself a finding about the gene and the disease.
neutropenia (1 paper, 2025). A decrease in the number of neutrophils found in the blood. "Myeloid deficiency syndromes include chronic idiopathic neutropenia (CIN), which is an acquired granulomatous disorder characterized by prolonged neutropenia, mild and asymptomatic clinical course, and affects mainly middle-aged women with the HLA-DRB1*1302 type." (PMID 40699662, 2025).
normal tension glaucoma (1 paper, 2010). "Allele frequencies of HLA-DRB1 in Japanese patients with normal tension glaucoma." (PMID 21031025, 2010).
Opportunistic infection (1 paper, 2015). An infection that is caused by a pathogen that would generally not be able to cause an infection in a host with a normal immune system. "In conclusion, this study is the largest cohort of patients that demonstrated a strong association between HLA-DRB1 and DQB1 alleles, especially HLA-DRB1*15:01, DRB1*16:02, DQB1*05:01 and DQB1*05:02, and disseminated opportunistic infection with acquired anti-IFN-γ autoantibody." (PMID 26011559, 2015).
Oral ulcer (1 paper, 2020). Erosion of the mucous mebrane of the mouth with local excavation of the surface, resulting from the sloughing of inflammatory necrotic tissue. "Besides HLA-DRB1*04, HLA-DRβ1*15 was significantly associated with the increased risk of developing oral ulcer (OR: 5.036, 95% CI: 1.029–24.638, p < 0.05)." (PMID 33644084, 2020). "Although most of the studies relate HLA-DRB1*15 with LN, our study had shown that the HLA-DRB1*15 allele was significantly associated with oral ulcers in Malay SLE patients." (PMID 33644084, 2020).
orofacial clefting (1 paper, 2023). "Although HLA‐DRB5 has not been associated with orofacial clefting or limb malformations, it is one of the HLA‐DRB cluster of genes in the HLA region of chromosome 6 and a paralog of the known oral cleft gene HLA‐DRB1, some transcripts of which may overlap." (PMID 37070724, 2023).
oropharyngeal cancer (1 paper, 2017). Carcinoma, predominantly squamous cell, arising from the epithelial cells of the oropharynx. "The HLA-DRB1*1301/HLA-DQA1*0103/HLA-DQB1*0603 haplotype has previously been associated with protection from oral and oropharyngeal cancer, particularly in HPV-positive cases (OR = 0.23, P = 1.6 × 10−6)." (PMID 28806749, 2017).
ovarian teratoma (1 paper, 2020). A non-seminomatous germ cell tumor arising from the ovary. "Our investigation indicated that HLA-A and HLA-DRB1 might be involved in mediating ovarian teratoma-associated NMDAR-E." (PMID 33160385, 2020).
parasite infections (1 paper, 2009). "D6S2883 is in strong linkage with the MHC class II gene HLA-DRB1, and heterozygosity at HLA-DRB1 has been implicated in resistance to both viral and parasite infections in humans." (PMID 19633717, 2009).
Pediatric onset (1 paper, 2025). Onset of disease manifestations before adulthood, defined here as before the age of 16 years, but excluding neonatal or congenital onset. "The association of LoHLAD with pediatric-onset autoimmune rheumatic disease at the HLA-A and HLA-DRB1 loci was not statistically significant." (PMID 39941587, 2025).
pertussis (1 paper, 2024). A contagious bacterial respiratory infection caused by Bordetella pertussis. "The results from our fine-mapping in Africa revealed an HLA-DRB3 variant as being most significant, whereas an HLA-DRB1 variant was highlighted as most associated with self-reported pertussis in the UK populations." (PMID 38740997, 2024). "Using immune cell expression quantitative trait loci datasets derived from African-ancestry samples from the 1000 Genomes Project, we found evidence of differential HLA-DRB1 expression correlating with inferred protection from pertussis following vaccination." (PMID 38740997, 2024). "We found HLA-DRB1 variants to be associated with increased PT-specific TFH cell activity, increased antibody production and ultimately protection against pertussis." (PMID 38740997, 2024).
plantar wart (1 paper, 2017). A wart in the plantar surface of the foot. "We identified two GWS associations with plantar wart, the first of which was with the HLA-DRB1 in the class II region." (PMID 28928442, 2017).
Q fever (1 paper, 2025). A bacterial infection caused by Coxiella burnetii. "In this study, the allele frequency of the HLA-DRB1 locus was analyzed in patients with acute Q fever and compared with a control group." (PMID 40333225, 2025). "TLR2 (Arg753Gln) and TLR4 (Asp299Gly, Thr399Ile) polymorphisms, along with HLA-DRB1 alleles, were analyzed for 38 patients with acute Q fever, 38 matched controls, and 121 blood donors." (PMID 40333225, 2025). "HLA-DRB1 variants may play a role in Q fever susceptibility, supporting the need for further investigation into their potential implications for vaccination and risk assessment." (PMID 40333225, 2025). "Specifically, the aim was to identify whether certain TLR2 or TLR4 polymorphisms, or specific HLA-DRB1 alleles, act as risk or protective factors for the development of acute Q fever." (PMID 40333225, 2025).
rectal cancer (1 paper, 2025). A primary or metastatic malignant neoplasm that affects the rectum. "A TCR specific to the PIK3CAE545K, restricted by HLA-DRB1*04:01, was also identified following IVS of memory CD4 + PBL from another patient, with rectal cancer." (PMID 41410746, 2025).
renal dysfunction (1 paper, 2021). "HLA-DRB1*03 was previously associated with renal dysfunction by four groups with a combined total of 1261 ESRD subjects and over 3000 controls." (PMID 33542305, 2021).
sarcoma (1 paper, 2023). A usually aggressive malignant neoplasm of the soft tissue or bone. "Recent studies have highlighted HLA-DRB1 as a potential early marker for sarcomas that is significantly enriched in various immune-related logical processes and pathways." (PMID 36918772, 2023).
scoliosis (1 paper, 2012). A congenital or acquired spinal deformity characterized by lateral curvature of the spine. "In patients with elbow contractures and scoliosis (sideways curving of the spine), an up-regulation of three inflammatory genes was found when compared with patients without those features, namely HLA-DRB1 and HLA-DRB5, (FC = 8.8, 7.1), and GZMK (FC = 1.3; FDR = 0%)." (PMID 22479353, 2012).
sensory impairment (1 paper, 2025). "While HLA-DRB1 * 01:01 allele decreased the spinal cord involvement and sensory impairment manifestation in Japanese MS patients, a reduction of brainstem symptoms was linked to HLA-DRB1 * 09:01 and HLA-DRB1 * 13:02." (PMID 39999097, 2025). "In addition, we studied the linkage of HLA-DRB1 and HLA-DQB1 allele polymorphisms and HLA-DRB1 ~ HLA-DQB1 haplotypes with different clinical features of MS, such as optic neuritis, sensory impairment, and brainstem symptoms in Jordanian MS patients." (PMID 39999097, 2025). "While the HLA-DRB1 * 03:01, HLA-DRB1 * 11:01, and HLA-DRB1 * 15:01 alleles were the most frequently observed in MS patients with sensory impairment, but they do not reach a statistically significant association." (PMID 39999097, 2025).
soft tissue sarcoma (1 paper, 2024). A malignant neoplasm arising from muscle tissue, adipose tissue, blood vessels, fibrous tissue, or other supportive tissues excluding the bones. "Compared to non-metastatic patients, the GREM2 and CTSS genes exhibited significantly higher expression levels, while TINAGL1, ACKR1, and HLA-DRB1 showed a tendency to increase in metastatic soft tissue sarcoma (SS); however, these differences were not statistically significant." (PMID 39735532, 2024).
tauopathy (1 paper, 2016). Neurodegenerative disorders involving deposition of abnormal tau protein isoforms (tau proteins) in neurons and glial cells in the brain. "In contrast, when the information of the anti-IgLON5 antibodies status is missing but the clinical history is compatible or the patient harbored the HLA-DRB1*1001 and HLA-DQB1*0501 alleles, then the diagnostic category of “probable anti-IgLON5-related tauopathy” should be applied." (PMID 27358064, 2016).
temporal lobe epilepsy (1 paper, 2025). A localization-related (focal) form of epilepsy characterized by recurrent seizures that arise from foci within the temporal lobe, most commonly from its mesial aspect. "Another study looked at the frequency of the HLA-DRB1*13:02 allele and found that it had significant genetic susceptibility for temporal lobe epilepsy associated with mesial hippocampal sclerosis; however, the significance was lost with Bonferroni correction." (PMID 40305305, 2025).
teratoma (1 paper, 2020). A non-seminomatous germ cell tumor characterized by the presence of various tissues which correspond to the different germinal layers (endoderm, mesoderm, and ectoderm). "The results showed that the numbers of HLA-A (+) and HLA-DRB1 (+) cells in the teratoma tissues were significantly larger in the NMDAR-E (+) patients than those in the controls." (PMID 33160385, 2020). "Additionally, the immunohistochemical data revealed that the aggregation of HLA-A (+) and HLA-DRB1 (+) cells was more apparent in the teratoma tissues of NMDAR-E patients compared with that in the tissues of controls." (PMID 33160385, 2020).
thalassemia (1 paper, 2024). An inherited blood disorder characterized by a decreased synthesis of one of the polypeptide chains that form hemoglobin. "In addition, in a study of thalassemia patients in Iranian, HLA-DRB1*15:03 allele frequency was significantly different between 59 alloimmunised and 205 non-alloimmunised patients (OR: 4.193; Pc = 0.0001)." (PMID 38593173, 2024).
toxoplasmosis (1 paper, 2020). A parasitic disease contracted by the ingestion or fetal transmission of toxoplasma gondii. "Moreover, based on the 51 common supertargets of the cohort and personalized approach the down-regulated genes HLA-DRA and HLA-DRB1 were found to be prominently involved in all seven highlighted pathways, while the up-regulated gene LAMB3 played an additional role in toxoplasmosis." (PMID 33273683, 2020).
uremia (1 paper, 2016). A clinical syndrome associated with the retention of renal waste products or uremic toxins in the blood. "HLA-DRB1 alleles seems to be more closely associated with uremia patients and should be more weighted in HLA matching during allocation of kidney transplants." (PMID 27780235, 2016). "Based on the statistical analysis of 1,464 uremia patients and 10,000 unrelated healthy individuals, we detected 23 HLA-A alleles, 49 HLA-B alleles and 17 HLA-DRB1 alleles." (PMID 27780235, 2016). "These HLA-DRB1 alleles may be closely associated with uremia." (PMID 27780235, 2016). "In this study, genotypes of HLA-A, HLA-B and HLA-DRB1 loci were collected from 1,464 uremia patients and 10,000 unrelated healthy individuals in Henan province of China." (PMID 27780235, 2016).
urticaria (1 paper, 2023). A vascular reaction of the skin characterized by erythema and wheal formation due to localized increase of vascular permeability. "HLA-DRB1*1302, HLA-DQB1*0609, and HLA-DPB1*0201 were found to be related to aspirin-induced urticaria." (PMID 38137494, 2023).
tumor (88 papers, 1997 to 2026). "In the myeloid cell compartment, we found seven clusters, from which clusters 1, 3, and 4 were tumor-associated macrophages (TAM) expressing genes such as HLA-DRB1 and CD14." (PMID 37501683, 2023). "There is association between high expression of HLA-DRB1 with increased tumor-infiltrating lymphocytes and therapeutic response in TNBC consistent with its reduced expression in our FSCN1CON." (PMID 34959629, 2021). "It is important to mention here that the mutational burden among HLA-DRB1 alleles in PanTT39 tumour was calculated as 8.8%." (PMID 30377343, 2019). "On the other hand, marked loss (p = 0.0002) of HLA-DRB1 expression was evident in the tumor tissues compared to the normal tonsillar tissues." (PMID 28383029, 2017). "Thus, an obese or overweight person with this mutated HLA-DRB1*11 allele has less risk of tumor cell escape from the HLA system." (PMID 34712820, 2021). "We examined cytokine secretion profiles (IL-2, IL-4, IL-6, and IFNG) from activated T cells (CD69, IL-2RA, CD38, and HLA-DRB1) to evaluate T-cell activation in the CM tumor microenvironment, revealing consistently low expression levels." (PMID 40959090, 2025). "Compared to other EC subtypes,EC4 exhibited elevated expression levels of multiple genes implicated in antigen presentation (HLADRB1,HLA-DRB5,and HLA-DRA),immune cell recruitment (SELP,LIFR, and ACKR1),and anti-tumor inflammation (CCL14,IFITM1)." (PMID 41394809, 2025). "Signature gene analysis of IFN‐Mac_CXCL9 revealed 108 significantly up‐regulated genes in tumour‐infiltrating cells including HLA‐A, HLA‐DRB1 and interferon‐regulated genes (CXCL9, CXCL10 and IL4I1)." (PMID 41275425, 2025). "It specifically highlights genes associated with antigen processing and presentation, such as HLA-B, HLA-A and HLA-DRB1 and their possible effects on tumour progression and immune evasion." (PMID 38660159, 2024). "The top 100 genes found to be co-expressed with CD74 were examined using GEPIA2.0, finding that the top five genes (HLA-DMA, HLA-DPA1, HLA-DPB1, HLA-DRA, and HLA-DRB1) were highly correlated with CD74 in most tumor types." (PMID 38582956, 2024). "This is mediated via the fucosylation and cell surface enrichment of HLA-DRB1 and induction of anti-tumor immunity." (PMID 36690875, 2023). "This is consistent with our finding that loss of glycosylation–fucosylation of HLA-DRB1 or EB1 abrogates its cell surface localization and impairs its ability to induce anti-tumor immunity." (PMID 36690875, 2023). "Levels of tumor fucosylation and total and fucosylated HLA-DRB1 in tumor cells were generally higher in anti-PD1 responders than in non-responders from Massachusetts General Hospital (MGH; n = 31) and the MD Anderson Cancer Center (MDACC; n = 11)." (PMID 36690875, 2023). "We reasoned that determining how HLA-DRB1 is regulated by fucosylation would provide important insight into its crucial role in l-fuc-triggered anti-tumor immunity." (PMID 36690875, 2023). "With the exception of one non-responder, the complete responder also exhibited significantly increased fucosylated HLA-DRB1 in tumor cells before treatment." (PMID 36690875, 2023). "HLA-DRB1 is the most polymorphic locus of HLA-II genes, it is mainly involved in the immune process of tumor body, mainly expressed on the surface of APC cells (macrophages, dendritic cells, and B cells)." (PMID 33761666, 2021). "The results showed that the expression of CCR5, CD3E, CD4, and HLA-DRB1 mRNAs in tumor tissues was significantly higher than that of normal tissues adjacent to the tumor." (PMID 34490269, 2021). "Note that and the significant gene HLA-DRB1 is also part of the Tumour Inflammation Signature (TIS)." (PMID 32545367, 2020).
tumor (continued). "Some key molecules, such as CALR, HLA-A, HLA-DRB1, PDIA3, HLA-DQB1, HLA-E, and TAP2, have been implicated in various types of cancers and emphasized their important values related to the tumor progression." (PMID 31258820, 2019). "Peptides that would bind to HLA-DRB1 were nevertheless incorporated, assuming >90% chance that an adequate number of tumour cells would still be able to present antigen via HLA-DRB1." (PMID 30377343, 2019). "Appreciable expression of HLA-DRB1 was evident in tumor adjacent normal appearing tonsillar tissues (black arrowheads)." (PMID 28383029, 2017). "While SARC-L1 tumor cells lack HLA-DRB1*0101 expression, a very lowexpression of HLA-A*0201 molecules was found on these cells." (PMID 28430664, 2017). "Additionally, ENHO was positively co-expressed with MHC class II presentation genes (including HLA-DMA, HLA-DOA, HLA-DPA1, HLA-DPB1, and HLA-DRB1), supporting its role in promoting anti-tumor immunity." (PMID 40647442, 2025). "Subsequent studies investigating tumor fucosylation, total/fucosylated HLA-DRB1 and CD4+ T cells as biomarkers will need to factor for clinical variables including therapies received before anti-PD1 therapy and pre-existing medical conditions as well as time from biopsy to anti-PD1 treatment." (PMID 36690875, 2023). "As a result, we found that CD163, CD74, S100A4, S100A12, HLA-DRA, and HLA-DRB1, which are usually highly expressed in myeloid cell, were also highly expressed in tumor cells of cluster 6; thus, we termed this cluster myeloid-like tumor cells." (PMID 37138326, 2023). "To assess how HLA-DRB1 glycosylation–fucosylation contributes to tumor suppression and itICs, we compared control- or EB1-knocked-down SW1 tumors reconstituted with WT or glycofucomutant (N46G) EB1 (confirmation of knockdown reconstitution and fucosylation by IB and LPD, respectively)." (PMID 36690875, 2023). "Differential expression analysis of pre- and post-treatment tumor-infiltrating MAIT cells revealed upregulation of the activation marker HLA-DRB1, the cytotoxic effector GZMH, and the chemokines CCL4 and CCL5 following anti-PD-1 therapy in both types of cancer." (PMID 32849590, 2020). "This suggests the importance of other factors that may mediate CRS, such as HLA‐DRB1 mismatching and tumor burden that we were able to identify for the first time as variables associated with grade ≥3 CRS in the contest of Haplo‐SCT with PT‐Cy." (PMID 31702882, 2020). "Thus, the M41 peptide has capability of binding to HLA-DRB1*1403, suggesting that the M41 peptide is promiscuous and would be available with tumour immunotherapy." (PMID 19277034, 2009). "However, cDCs in the PI3K/mTORi+PD‐1i‐treated tumours upregulated expression of genes related to antigen presentation via major histocompatibility complex class II (MHC II) (HLA‐DRB1, HLA‐DQB1, HLA‐DPB1, HLA‐DQB2, CD74) compared with cDCs in tumours treated with PD‐1i, PI3K/mTORi‐ or vehicle." (PMID 38711203, 2024). "Because we were unable to control for these confounders in our specimens, it is unclear how they may have impacted tumor and HLA-DRB1 fucosylation and CD4+ T cell biology and thus the strength of correlations between these markers and responsiveness to treatment." (PMID 36690875, 2023). "Furthermore, a number of interferon (IFN) response genes (BST2, CD74, HLA-DMA, HLA-DPB1, HLA-DQB1, HLA-DRA, HLA-DRB1, and IRF8) were upregulated in C10 compared to the other clusters, whereas genes associated with tumor suppression and apoptosis (TFF1 and TFF2) were downregulated." (PMID 37370788, 2023). "Furthermore, the downregulation of HLA-DRB1 is not only associated with metastasis and poor prognosis of CM patients, but also might accelerate the change of TME from tumor suppressive to tumor friendly." (PMID 36129956, 2022).